PTDSS2 (phosphatidylserine synthase 2)
Description:
Catalyzes a base-exchange reaction in which the polar head group of phosphatidylethanolamine (PE) or phosphatidylcholine (PC) is replaced by L-serine. Catalyzes the conversion of phosphatatidylethanolamine and does not act on phosphatidylcholine. Can utilize both phosphatidylethanolamine (PE) plasmalogen and diacyl PE as substrate and the latter is six times better utilized, indicating the importance of an ester linkage at the sn-1 position (By similarity). Although it shows no sn-1 fatty acyl preference, exhibits significant preference towards docosahexaenoic acid (22:6n-3) compared with 18:1 or 20:4 at the sn-2 position (By similarity).
Synonyms: PSS2
Tractability: Antibody: UniProt predicts a signal peptide or a membrane-spanning region. PROTAC: ubiquitination databases record sites on it; its protein half-life has been measured.
Target class: Enzyme; Transferase
Gene: Protein-coding gene on chromosome 11 (448,268 to 491,399, forward strand). Ensembl gene ENSG00000174915.
Subcellular location: Endoplasmic reticulum membrane
Pathways (Reactome):
Metabolism: Synthesis of PS
Gene Ontology:
Molecular function: L-serine-phosphatidylethanolamine phosphatidyltransferase activity; transferase activity; CDP-diacylglycerol-serine O-phosphatidyltransferase activity
Biological process: phosphatidylserine biosynthetic process
Cellular component: endoplasmic reticulum membrane; membrane
Genetic constraint (gnomAD): Loss-of-function variants: 39 observed, 63.53 expected, observed/expected ratio (o/e) 0.61, 90% interval 0.47 to 0.8. The upper end of that interval is the gene's LOEUF score, 0.8, which puts it in group 3 of 6, group 1 being the genes least tolerant of losing a copy. Missense variants: 482 observed, 631.36 expected, observed/expected ratio (o/e) 0.76, 90% interval 0.71 to 0.82. Synonymous variants: 294 observed, 269.03 expected, observed/expected ratio (o/e) 1.09, 90% interval 0.99 to 1.2.
Homologues: Orthologues: macaque PTDSS2 (97% identical), pig PTDSS2 (91% identical), dog PTDSS2 (90% identical), guinea pig PTDSS2 (87% identical), mouse Ptdss2 (86% identical), rat Ptdss2 (86% identical), tropical clawed frog ptdss2 (77% identical), zebrafish ptdss2 (74% identical), Caenorhabditis elegans pssy-1 (30% identical), Caenorhabditis elegans pssy-2 (29% identical). Paralogues in human: PTDSS1 (30% identical).
Diseases named in the same sentence as PTDSS2 in open-access papers:
PTDSS2 is named in the same sentence as 10 diseases in open-access papers, as found by Europe PMC text mining. Sharing a sentence is not in itself a finding about the gene and the disease. The quoted sentences say what the papers report.
breast carcinoma (2 papers, 2022). "Further analysis revealed that cells with low ATP11B expression and high PTDSS2 expression (ATP11BloPTDSS2hi cells) were associated with poor prognosis and enhanced metastasis in breast cancer patients in general." (PMID 35025764, 2022). "At this point, how PTDSS2 and miR-613 methylation aids in 27-HC-mediated breast cancer progression remains inexplicable." (PMID 35360070, 2022). "Therefore, we searched various databases to identify whether any drugs can have effects on the expression of ATP11B and PTDSS2 during the treatment of patients with breast cancer." (PMID 35025764, 2022). "In our efforts to identify drugs that might inhibit BRCA1-deficient tumor growth and metastasis, we found that paclitaxel or docetaxel treatment can reverse the expression pattern of ATP11B and PTDSS2 in breast cancers and significantly inhibit cancer metastasis." (PMID 35025764, 2022). "Our study demonstrates that low levels of ATP11B expression and high levels of PTDSS2 expression promote breast cancer metastasis by increasing nonapoptotic PS populations on the outer leaflet of the cell membrane." (PMID 35025764, 2022).
B cell lymphomas (1 paper, 2024). "Our screen revealed that B cell lymphoma is highly dependent on PTDSS1 despite intact PTDSS2 expression." (PMID 38048228, 2024). "One possible explanation for the high PTDSS1 dependency is that B cell lymphomas may distinguish the difference in the acyl-chain species of PS synthesized by PTDSS1 and PTDSS2." (PMID 38048228, 2024). "However, this is not the case for B cell lymphomas, which greatly required PS synthesis by PTDSS1, but not PTDSS2, for their growth in both in vitro culture and in vivo." (PMID 38048228, 2024).
glioblastoma (1 paper, 2023). The most malignant astrocytic tumor (WHO grade IV). "The significance of PTDSS2 in glioblastoma tumorigenesis may be explained by the role of PS, a phospholipid located in the inner bilayer of the cell membrane." (PMID 37046844, 2023). "The expression of PTDSS2 in glioblastoma tumors does not differ from that in healthy brain tissue." (PMID 37046844, 2023).
Obesity (1 paper, 2024). Accumulation of substantial excess body fat. "It is suspected that PTDSS2 and PS may be related to obesity by influencing thermogenesis or another process that needs further exploration for a better understanding of obesity." (PMID 39409074, 2024).
cancer (5 papers, 2015 to 2024). A tumor composed of atypical neoplastic, often pleomorphic cells that invade other tissues. "Another study suggested that cancer cell populations with PTDSS2 deletion are highly susceptible to PTDSS1 inhibition." (PMID 38048228, 2024). "A PTDSS1-specific inhibitor was recently developed based on synthetic lethal activity against cancer cells harboring a genetic deletion of PTDSS2, in which PTDSS1 inhibition causes profound loss of cellular PS and acute cell death." (PMID 38048228, 2024). "Mechanistically, its low expression or deficiency together with high expression of Ptdss2 increased the PS population on the outer leaflet of the cell membrane and generated a global immunosuppressive signal, leading to cancer metastasis." (PMID 35025764, 2022). "The 27-HC-mediated transcriptional downregulation of PTDSS2 is well correlated with the PTDSS2 deletion phenotype observed in many cancers." (PMID 35360070, 2022). "Our further analysis revealed that in Brca1-WT cancer cells, ATP11b and Ptdss2 signaling also plays similar roles in cancer metastasis." (PMID 35025764, 2022). "But interestingly, it has been found that the PTDSS2 gene has been deleted in few cancers." (PMID 35360070, 2022). "In this regard, future studies should focus on addressing the expression status and activity of PS synthases PTDSS1 and PTDSS2 in different tumors, which might reveal important information in terms of mis-regulation of these enzymes in cancer." (PMID 26462157, 2015).
tumor (4 papers, 2021 to 2024). "Accordingly, potent and selective PTDSS1 inhibitors were developed, and their application in PTDSS2-deficient tumor models resulted in tumor regression." (PMID 38573347, 2024). "In hepatocellular carcinoma, higher PTDSS2 expression in the tumor is associated with a poorer prognosis." (PMID 39409074, 2024). "When considering the expression of two genes, ATP11B and PTDSS2, simultaneous low ATP11B expression and higher PTDSS2 expression are associated with worse prognoses compared to patients with higher ATP11B and lower PTDSS2 expression in the tumor." (PMID 39409074, 2024). "In vitro and in vivo studies have shown that these inhibitors are effective against tumors with a deletion in the tumor-suppressive locus 11p15.5, where the PTDSS2 gene is located, representing the second isoform of phosphatidylserine synthase." (PMID 39409074, 2024). "Because the PTDSS2 protein level was stably elevated in both Brca1-MT mammary gland and tumor tissues in Brca1-MT mice, we conducted a promoter luciferase reporter assay, and the data revealed that the Ptdss2 promoter is negatively regulated by Brca1." (PMID 35025764, 2022). "Importantly, increased immunogenicity translated into protection against PTDSS2-WT tumor cells in the surrounding, indicating the induction of overall protective immunity." (PMID 38573347, 2024). "In this study, we demonstrated that no expression or low expression of ATP11B in conjunction with high expression of PTDSS2, which was negatively regulated by BRCA1, markedly accelerates tumor metastasis." (PMID 35025764, 2022). "Western blot analysis showed that only the PTDSS2 protein level was stably elevated from both Brca1-MT mammary glands and tumor tissues of Brca1-MSK mice, but not PTDSS1." (PMID 35025764, 2022). "Disrupting PTDSS1 activity may therefore specifically affect tumor cells rather than untransformed cells that still express PTDSS2 to produce PS." (PMID 38573347, 2024).
PTDSS2 also shares sentences with these, for which no sentence is quoted: colorectal cancer (1 paper); hepatocellular carcinoma (1); ovarian carcinoma (1); uveitis (1).